GPR22 (G protein-coupled receptor 22)
Description:
Orphan G protein-coupled receptor. Seems to act through a G(i)/G(o) mediated pathway. May be involved in ciliogenesis (By similarity).
Tractability: Small molecule: it belongs to a druggable protein family. Antibody: UniProt places it where antibodies can reach, with medium confidence; UniProt predicts a signal peptide or a membrane-spanning region; its Gene Ontology location is reachable by antibodies, with medium confidence.
Target class: Family A G protein-coupled receptor; Membrane receptor
Gene: Protein-coding gene on chromosome 7 (107,470,018 to 107,476,314, forward strand). Ensembl gene ENSG00000172209.
Subcellular location: Cell membrane
Gene Ontology:
Molecular function: G protein-coupled receptor activity
Biological process: cellular response to hormone stimulus; G protein-coupled receptor signaling pathway
Cellular component: plasma membrane; membrane
Genetic constraint (gnomAD): Loss-of-function variants: 10 observed, 25.62 expected, observed/expected ratio (o/e) 0.39, 90% interval 0.24 to 0.66. The upper end of that interval is the gene's LOEUF score, 0.66, which puts it in group 2 of 6, group 1 being the genes least tolerant of losing a copy. Missense variants: 263 observed, 398.37 expected, observed/expected ratio (o/e) 0.66, 90% interval 0.6 to 0.73. Synonymous variants: 149 observed, 135.13 expected, observed/expected ratio (o/e) 1.1, 90% interval 0.96 to 1.26.
Homologues: Orthologues: chimpanzee GPR22 (100% identical), macaque GPR22 (100% identical), dog GPR22 (99% identical), pig GPR22 (99% identical), rabbit GPR22 (98% identical), mouse Gpr22 (97% identical), rat Gpr22 (96% identical), zebrafish gpr22a (76% identical), zebrafish gpr22b (73% identical), Drosophila melanogaster CrzR (14% identical), Caenorhabditis elegans daf-38 (12% identical). Paralogues in human: CCKBR (17% identical), CCKAR (17% identical), QRFPR (16% identical), OXTR (15% identical), AVPR1B (14% identical), GNRHR (14% identical), HCRTR1 (14% identical), HCRTR2 (14% identical), NPFFR1 (14% identical), NPFFR2 (14% identical), AVPR1A (14% identical), GALR3 (14% identical), and 4 more.
Diseases named in the same sentence as GPR22 in open-access papers:
GPR22 is named in the same sentence as 13 diseases in open-access papers, as found by Europe PMC text mining. Sharing a sentence is not in itself a finding about the gene and the disease. The quoted sentences say what the papers report.
acute myocardial infarction (2 papers, 2024 to 2025). Necrosis of the myocardium, as a result of interruption of the blood supply to the area. "Acute myocardial infarction (AMI) was induced by left coronary artery ligation in eight-week-old male GPR22 transgenic mice, followed by histopathological and biochemical examination four weeks post-AMI induction." (PMID 38816768, 2024). "H&E staining revealed an increase in infarct area in mice with AMI, whereas myocardial infarction induced by AMI was attenuated in mice overexpressing myocardial GPR22." (PMID 38816768, 2024). "Overexpression of GPR22 in cardiomyocytes ameliorates myocardial infarction and collagen deposition in mice post-AMI through regulating myocardial activation of PI3K-Akt signaling." (PMID 38816768, 2024). "Histopathological examinations revealed a protective effect of GPR22 overexpression in attenuating myocardial infarction in mice with AMI." (PMID 38816768, 2024). "Cardiomyocyte-specific overexpression of GPR22 in mice resulted in acute myocardial infarction." (PMID 40362725, 2025). "The present study, utilizing a transgenic mouse model, further indicated an increased expression of GPR22 in cardiomyocytes and showed that upregulating its downstream signaling pathways could ameliorate myocardial injury following acute myocardial infarction (AMI)." (PMID 38816768, 2024).
cardiac hypertrophy (2 papers, 2017 to 2021). "Next generation sequence (NGS) analysis indicated a modulation of the expression levels of several cardiac hypertrophy-associated genes, including GPR22, Myh7, Nppa, P2RX4, and Npy by MFE." (PMID 34579143, 2021). "In addition, the role of GPR22 in MFE-induced cardiac hypertrophy is still unclear and needs to be further investigated." (PMID 34579143, 2021).
diabetes (2 papers, 2021 to 2024). "Concurrently, reduced expression of GPR22 was observed in the myocardium of rodents with ventricular pressure overload and diabetes." (PMID 38816768, 2024). "GPR22 is an orphan GPCR expressed in brains and hearts, while its expression level is associated with cardiovascular damage in diabetes." (PMID 38816768, 2024). "GPR22, a G protein-coupled receptor, whose myocardial expression is regulated by the induction of diabetes in rats." (PMID 34579143, 2021).
heart failure (2 papers, 2017 to 2024). Inability of the heart to pump blood at an adequate rate to meet tissue metabolic requirements. "Previous studies have suggested a protective role of GPR22 in mechanical cardiac stress, as loss of its expression increases susceptibility to heart failure post-ventricular pressure overload." (PMID 38816768, 2024).
Alzheimer disease (1 paper, 2024). A progressive, neurodegenerative disease characterized by loss of function and death of nerve cells in several areas of the brain leading to loss of cognitive function such as memory and language. "Recent studies also indicated a decrease in GPR22 expression in the brain of Alzheimer’s disease (AD) patients." (PMID 38816768, 2024).
ischemia (1 paper, 2024). A hypoperfusion of the BLOOD through an organ or tissue caused by a PATHOLOGIC CONSTRICTION or obstruction of its BLOOD VESSELS, or an absence of BLOOD CIRCULATION. "Myocardial ischemic stress downregulates cardiac expression of GPR22, whereas overexpression of GPR22 in cardiomyocytes upregulates Akt signaling, downregulates ERK activation, and mitigates ischemia-induced myocardial injury." (PMID 38816768, 2024).
myocardial ischemia (1 paper, 2024). A disorder of cardiac function caused by insufficient blood flow to the muscle tissue of the heart. "Similarly, compared to wild-type mice, areas of myocardial ischemia-induced collagen deposition were reduced in mice with GPR22 overexpression." (PMID 38816768, 2024).
osteoarthritis (1 paper, 2022). A noninflammatory degenerative joint disease occurring chiefly in older persons, characterized by degeneration of the articular cartilage, hypertrophy of bone at the margins and changes in the synovial membrane. "GPR22 has also been implicated in osteoarthritis in humans through GWAS." (PMID 36047852, 2022).
GPR22 also shares sentences with these, for which no sentence is quoted: cancer (1 paper); glioma (1); high blood pressure (1); ischemic heart diseases (1); tumour (1).